RN7SKP248 (RN7SK pseudogene 248)
Gene: Miscellaneous RNA gene on chromosome 4 (90,370,123 to 90,370,427, forward strand). Ensembl gene ENSG00000252087.
Homologues: Orthologues: chimpanzee 7SK (99% identical), mouse Gm55435 (48% identical), mouse Gm56266 (38% identical). Paralogues in human: RN7SKP211 (58% identical), RN7SKP71 (57% identical), RN7SKP189 (57% identical), RN7SKP25 (57% identical), RN7SKP163 (57% identical), RN7SKP204 (57% identical), RN7SKP255 (57% identical), RN7SKP203 (56% identical), RN7SKP296 (56% identical), RN7SKP153 (56% identical), RN7SKP170 (56% identical), RN7SKP102 (56% identical), and 284 more.